MYEF2 (myelin expression factor 2)
Description:
Transcriptional repressor of the myelin basic protein gene (MBP). Binds to the proximal MB1 element 5'-TTGTCC-3' of the MBP promoter. Its binding to MB1 and function are inhibited by PURA (By similarity).
Synonyms: MEF-2; MyEF-2; KIAA1341; FLJ11213; HsT18564; MST156; MSTP156
Tractability: PROTAC: UniProt records ubiquitination sites on it; ubiquitination databases record sites on it; its protein half-life has been measured.
Gene: Protein-coding gene on chromosome 15 (48,134,632 to 48,178,353, reverse strand). Ensembl gene ENSG00000104177.
Subcellular location: Nucleus
Subcellular location (Human Protein Atlas): Nucleoplasm; Cytosol
Gene Ontology:
Molecular function: RNA binding; nucleic acid binding
Biological process: myotube differentiation; neuron differentiation
Cellular component: nucleus
Genetic constraint (gnomAD): Loss-of-function variants: 32 observed, 64.69 expected, observed/expected ratio (o/e) 0.49, 90% interval 0.37 to 0.66. The synonymous counts are far from expectation, so gnomAD's model fits this gene poorly and the ratio says little. Missense variants: 599 observed, 735.7 expected, observed/expected ratio (o/e) 0.81, 90% interval 0.76 to 0.87. Synonymous variants: 179 observed, 230.09 expected, observed/expected ratio (o/e) 0.78, 90% interval 0.69 to 0.88.
Homologues: Orthologues: chimpanzee MYEF2 (99% identical), macaque MYEF2 (99% identical), rabbit MYEF2 (96% identical), pig MYEF2 (95% identical), dog MYEF2 (92% identical), rat Myef2 (91% identical), mouse Myef2 (90% identical), guinea pig MYEF2 (85% identical), mouse Myef2l (74% identical), tropical clawed frog myef2 (69% identical), zebrafish myef2 (63% identical), Drosophila melanogaster rump (33% identical), and 1 more. Paralogues in human: HNRNPM (53% identical).
Diseases named in the same sentence as MYEF2 in open-access papers:
MYEF2 is named in the same sentence as 21 diseases in open-access papers, as found by Europe PMC text mining. Sharing a sentence is not in itself a finding about the gene and the disease. The quoted sentences say what the papers report.
melanoma (5 papers, 2017 to 2024). A malignant, usually aggressive tumor composed of atypical, neoplastic melanocytes. "MYEF2 expression was upregulated in colorectal cancer, leukaemia, liver cancer, melanoma and ovarian cancer." (PMID 36658471, 2023). "In addition, MYEF2 is assumed to bind to H1.0 histone mRNA and promote its packaging into extracellular vesicles in melanoma cells, which promotes tumourigenesis." (PMID 37556355, 2023). "Another is the myelin expression factor 2 (MYEF-2), first described for its ability to repress transcription of the gene encoding myelin basic protein, but recently found in EVs released by melanoma cells, bound to H1.0 histone mRNA." (PMID 28937658, 2017). "For example, the Myelin expression factor 2 (MYEF-2), already known as a transcriptional repressor of the gene for the myelin basic protein, was also found in melanoma cell-derived EVs, where it is bound to the H1.0 histone mRNA." (PMID 39194524, 2024).
schwannoma (2 papers, 2023). A benign, usually encapsulated slow growing tumor composed of Schwann cells. "Another gene, Myef2, is a transcriptional repressor of the myelin basic protein gene, the expression of which is usually up-regulated in nerve sheath myxomas and schwannomas." (PMID 36669641, 2023). "In addition, current studies have confirmed that MYEF2 is involved in the development of lung adenocarcinoma and schwannoma." (PMID 36658471, 2023).
liver cancer (1 paper, 2023). An epithelial or non-epithelial malignant neoplasm that arises from the liver. "In the present study, we first used a public database integrating a large number of samples to discover and identify a potential liver cancer marker, MYEF2, which improved the quality and credibility of the research to better perform subsequent experimental studies." (PMID 36658471, 2023).
lung carcinoma (1 paper, 2020). "The upregulated genes included CYP4F3, IL1RL1, PTGS2, and CXCL8, which are related to inflammation; HKDC1, MYEF2 and CYP1A1, which are related to hepatocarcinoma or lung carcinoma; and SLC7A11 and NEFM, which are related to neuronal damage." (PMID 33247188, 2020).
lymphoma (1 paper, 2023). A malignant (clonal) proliferation of B- lymphocytes or T- lymphocytes which involves the lymph nodes, bone marrow and/or extranodal sites. "MYEF2 has been confirmed to be a biomarker of smouldering subtypes in the adult T cell leukaemia/lymphoma (ATLL) classification." (PMID 37556355, 2023).
myocardial ischemia (1 paper, 2023). A disorder of cardiac function caused by insufficient blood flow to the muscle tissue of the heart. "MYEF2 has also been reported to be associated with haematopoietic stem cell generation and myocardial ischemia–reperfusion injury." (PMID 37556355, 2023).
partial albinism (1 paper, 2022). "For example, SLC24A5, MYEF2, and CTXN2 gene variations have been associated with differences in skin pigmentation, partial albinism, and retinal pigment; SLC12A1 plays a key role in concentrating urine, and its defects result in some Bartter-like syndromes." (PMID 35440892, 2022).
prediabetes (1 paper, 2020). "In contrast, carbonic anhydrase 1 (CAH1) and polypeptides from myelin expression factor 2 (MYEF2) 31 and kininogen-1 (KNG1) 32 showed specific abnormalities only in T2D but not in prediabetes." (PMID 32089734, 2020).
prostate carcinoma (1 paper, 2014). A carcinoma that arises from epithelial cells of the prostate gland. "Our results underline the importance of the gene for prostate cancer, although no direct relationship between MYEF2 and the cancer had been established yet." (PMID 25151146, 2014). "In the results, two of the four genes (TUBB6, PARM1) are supported by literature for their roles in prostate cancer; nonetheless, the other two (SLC25A22, MYEF2) are less known." (PMID 25151146, 2014). "Since they are co-interacting with PARM1 and MYEF2, ESR1 and NR3C2 may also participate in prostate cancer along with the existent/potential targets." (PMID 25151146, 2014).
cancer (4 papers, 2014 to 2023). A tumor composed of atypical neoplastic, often pleomorphic cells that invade other tissues. "In the bioinformatics analysis phase of this study, We preliminarily found that MYEF2 was abnormally expressed in various malignant tumors, and MYEF2 was significantly overexpressed in HCC tissues compared with normal liver tissues." (PMID 36658471, 2023). "The Cancer Genome Atlas database was used to further validate and analyse the value of MYEF2." (PMID 36658471, 2023). "Furthermore, the possible carcinogenesis role of MYEF2 has been proposed; however, its performance in cancer is still unknown and it should be evaluated in further studies." (PMID 35449091, 2022). "It is also noteworthy that although the other two genes we identified (SLC25A22 and MYEF2) do not possess direct therapeutic utilities at present, they may somehow implicate theoretical clues for cancer therapies." (PMID 25151146, 2014).
tumor (2 papers, 2023). "MYEF2 expression is significantly associated with the tumour stage, histological grade and TNM stage." (PMID 36658471, 2023). "Further molecular, cellular, and animal model studies should be performed to achieve a comprehensive understanding of the mechanism of MYEF2 in immune infiltration and tumor progression in GBMs." (PMID 37556355, 2023). "Our study suggests that MYEF2 expression negatively correlates with T cell exhaustion and tumor progression, rendering it a potentially valuable prognostic biomarker for GBM." (PMID 37556355, 2023). "We found that the expression of MYEF2 was higher in HCC patients with late tumor stage, higher malignancy and poorer differentiation." (PMID 36658471, 2023). "The MYEF2 expression level, tumour stage, T stage, lymph node metastasis and distant metastasis were risk factors affecting the prognosis of patients with HCC." (PMID 36658471, 2023). "We screened 423 studies to assess MYEF2 expression in different tumours from the ONCOMINE database." (PMID 36658471, 2023). "Our current study showed that MYEF2 might be a novel tumour marker for HCC." (PMID 36658471, 2023). "Based on these results, we concluded that MYEF2 expression is increased in HCC tissues and cell lines and may be related to tumour pathology or the prognosis of patients with HCC." (PMID 36658471, 2023).
MYEF2 also shares sentences with these, for which no sentence is quoted: colorectal cancer (2 papers); breast carcinoma (1); glioblastoma (1); hepatocellular carcinoma (1); leukaemia (1); lung adenocarcinoma (1); multiple myeloma (1); nerve sheath myxomas (1); ovarian carcinoma (1); thyroid cancer (1).